IGFBP2 (insulin like growth factor binding protein 2)
Diseases named in the same sentence as IGFBP2 in open-access papers (continued):
Sharing a sentence is not in itself a finding about the gene and the disease.
non-small cell lung carcinoma (5 papers, 2013 to 2024). A group of at least three distinct histological types of lung cancer, including non-small cell squamous cell carcinoma, adenocarcinoma, and large cell carcinoma. "In non-small cell lung carcinoma, in vitro studies indicate that both soluble and membrane-associated IGFBP-2 competes with IGF receptors for ligand binding and, thus, are likely to be important determinants of IGF responsiveness." (PMID 27215343, 2016). "Furthermore, intrinsic resistance to dasatinib in a panel of non-small-cell lung cancer cell lines has been causally linked to the upregulation of Insulin-like growth factor (IGF)-binding protein-2 (IGFBP2) which acts as a carrier protein for the IGF ligands." (PMID 28842319, 2018). "Alterations in IGFBP2 expression are associated with resistance to both anti-IGF1R agents and dasatinib in rhabdomyosarcoma and non-small cell lung cancer cells, respectively." (PMID 33673232, 2021). "Particularly, loss of IGFBP2 is associated with resistance to anti-IGF1R treatment due to hyperactivation of IGF signaling in rhabdomyosarcoma, while overexpression of IGFBP2 drives dasatinib resistance through activation of FAK in non-small cell lung cancer cells." (PMID 33673232, 2021). "In terms of mechanism, IGFBP2/ITGA5 enhances the expression of CXCL1 by activating STAT3, thereby promoting gefitinib resistance in non-small cell lung cancer." (PMID 38918360, 2024).
rhabdomyosarcoma (5 papers, 2015 to 2025). A rare aggressive malignant mesenchymal neoplasm arising from skeletal muscle. "However, down-regulation of IGFBP2 in rhabdomyosarcoma is associated with resistance to IGF1R therapy." (PMID 25774149, 2015). "Increased IGFBP2 expression correlates with tumor severity in rhabdomyosarcoma (RMS)." (PMID 32093404, 2020).
acute lymphoblastic leukemia (4 papers, 2013 to 2017). Leukemia with an acute onset, characterized by the presence of lymphoblasts in the bone marrow and the peripheral blood. "IGFBP-2 is critical for chemoresistance in acute lymphoblastic leukemia cells." (PMID 28977895, 2017). "IGFBP2 is highly expressed in certain human AML and acute lymphoblastic leukemia (ALL) cells." (PMID 24191913, 2013).
anorexia nervosa (4 papers, 2019 to 2025). A disorder most often seen in adolescent females characterized by a refusal to maintain a minimally normal body weight, an intense fear of gaining weight, a disturbance in body image, and, in postmenarcheal females, the development of amenorrhea. "In contrast, IGFBP2 concentrations are high in patients with anorexia nervosa." (PMID 32532003, 2020). "In obese patients circulating IGFBP2 levels are reduced and increased in patients with anorexia nervosa, with a negative correlation with BMI in normal pediatric subjects and adults." (PMID 34975768, 2021).
Anxiety (4 papers, 2022 to 2026). Intense feelings of nervousness, tension, or panic often arise in response to interpersonal stresses. "Therefore, these two circRNAs (mmu_circ_0008937 and hsa_circ_0058195) derived from homologous genes (Igfbp2/IGFBP2) might be associated with anxiety after TBI." (PMID 35918398, 2022). "It was demonstrated that the circRNA insulin-like growth factor binding protein 2 (circIGFBP2) played a key role in the development of anxiety-like behaviors following traumatic brain injury by impairing mitochondrial function and increasing oxidative stress." (PMID 40581642, 2025). "Importantly, Igfbp2 overexpression did not affect locomotor activity or foot‐shock thresholds, nor did it induce anxiety‐like behavior." (PMID 40801458, 2025). "Notably, Igfbp2 downregulation did not affect locomotor activity, foot shock thresholds, or induce anxiety‐like behavior, nor did it alter the number of the PVT neurons." (PMID 40801458, 2025).
atherosclerosis (4 papers, 2023 to 2024). A disease characterized by the build-up of fatty material and calcium deposition in the arterial wall resulting in partial or complete occlusion of the arterial lumen. "We were able to confirm three additional proteins associated with CIMT using our age-sex adjusted model namely GFRA1, IGFBP2 and GHR, which have been all reported to be linked to CVD, mortality, and atherosclerosis." (PMID 38811951, 2024). "In addition, IGFBP-2 enhances the migration and proliferation of vascular smooth muscle cells (VSMC), this process is associated with the development of atherosclerosis." (PMID 36970368, 2023). "IGFBP-2 plays a crucial role in regulating mitogen-activated protein kinase (MAPK) pathway, which is a driver of atherosclerosis and involved in inflammatory signaling and oxidative stress." (PMID 36970368, 2023). "Moreover, IGFBP-2 regulates the phosphatidylinositol 3-kinase (PI3K)/alpha serine/threonine-protein kinase (Akt) signaling pathway, which has a fundamental role in the pathological processes of atherosclerosis." (PMID 36970368, 2023).
chronic kidney disease (4 papers, 2012 to 2025). Impairment of the renal function secondary to chronic kidney damage persisting for three or more months. "Previous studies have reported increased IGFBP2 concentrations in chronic renal failure." (PMID 23781310, 2012).
endothelial dysfunction (4 papers, 2021 to 2025). In vascular diseases, endothelial dysfunction is a systemic pathological state of the endothelium (the inner lining of blood vessels) and can be broadly defined as an imbalance between vasodilating and vasoconstricting substances produced by (or acting on) the endothelium. "The pathophysiology of CE stroke is related to endothelial dysfunction and coagulation activation, processes in which IGFBP-2 has been involved." (PMID 38673963, 2024). "IGFBP-2 could be a biomarker of embolic IS and a new therapeutic target involved in clot formation and endothelial dysfunction." (PMID 38673963, 2024). "In particular, IGFBP-2 emerges as a potential biomarker of embolic IS etiology involved in processes intrinsically related to IS pathophysiology, such as clot formation and endothelial dysfunction." (PMID 38673963, 2024). "IGFBP2 has been shown to directly regulate endothelial cell function, and alterations in its balance may lead to endothelial dysfunction." (PMID 37904201, 2023).
fetal growth restriction (4 papers, 2018 to 2024). A fetus that does not grow beyond the 10th percentile of conventionally accepted weight for gestational age. "Additionally, intrauterine growth retardation is associated with a decrease in IGF-I and an increase in IGFBP-1 and IGFBP-2 levels in fetal blood." (PMID 32635165, 2020).
Hypertension (4 papers, 2013 to 2024). The presence of chronic increased pressure in the systemic arterial system. "Altogether, we found nine genes (Cst3, Cyp11b2, Ephx2, Fn1, Igfbp2, P2rx4, Prkcd, RT1-Ba, and Sult1a1) annotated in the RGD as associated with hypertension in this group." (PMID 26822062, 2016). "Whereas the association of IGFBP2 level with hypertension were not adjusted for lipid levels." (PMID 29100429, 2017).
liver cancer (4 papers, 2012 to 2025). An epithelial or non-epithelial malignant neoplasm that arises from the liver. "Since the liver, bile duct, and pancreas have a common embryologic origin, AAT and IGFBP2 have the same limitations as CA19-9 in differentiating between liver cancer and cholangiocarcinoma." (PMID 36712921, 2023).
lupus (4 papers, 2021 to 2024). "Increased serum IGFBP-2 levels were detected in patients with systemic lupus erythematosus, rheumatoid arthritis, or inflammatory bowel disease." (PMID 37720230, 2023). "Signaling by the PI3K/Akt/mTOR pathway profoundly affects mRNA translation through phosphorylation of downstream targets such as 4E-BP and RPS6KB1; we further explored the level of phosphorylation of 4E-BP1 and RPS6KB1 in lymphocytes of mouse models of lupus with IGFBP2 blockade treatment." (PMID 36008635, 2022). "Some studies have confirmed that IGFBP2 is a promising biomarker for systemic lupus erythematosus (SLE) and LN." (PMID 38570749, 2024). "And, a blockade of IGFBP2 elevated the ratio of Tregs inhibits the proliferation and activation of CD4+ T cells, thereby achieving the possibility of inhibiting the progression of lupus (P < 0.05)." (PMID 36008635, 2022). "Moreover, the mTOR signaling pathway is regulated by IGFBP2 in cancer; we next examined the effect on AKT/mTOR signaling pathway with IGFBP2 blockade in mouse models of lupus." (PMID 36008635, 2022). "Furthermore, the glomerular IGFBP2 expression was shown to be increased in animal models of anti-glomerular basement membrane glomerulonephritis and MRL/lpr lupus." (PMID 33641616, 2021).
malnutrition (4 papers, 2018 to 2025). Inadequate nutrition resulting from poor diet, malabsorption, or abnormal nutrient distribution. "Elevated IGFBP-2 was recently found to be associated with malnutrition, and the observed decrease in IGFBP-2 levels following nutritional intervention is potentially reflective of an improved nutrition status." (PMID 35334853, 2022). "Malnutrition within the CHAIN cohort children likely underlies increased levels of IGFBP2 and its consequences could be perturbed metabolism and growth impairments." (PMID 41315420, 2025).
medulloblastoma (4 papers, 2013 to 2025). A malignant, invasive embryonal neoplasm arising from the cerebellum. "IGFBP2 plays an important role in medulloblastoma proliferation, migration, signal transduction, and activation of transcription protein activity and epithelial-to-mesenchymal transition marker levels." (PMID 40075946, 2025). "Despite the large volume of literature implicating IGFBP2 in growth and metastasis of many types of cancer, there is a dearth of published research on IGFBP2 in medulloblastoma." (PMID 37029430, 2023). "Both studies were small in sample size and did not include molecular subgroup classification, therefore we determined that based on our cytokine array results, the role and function of IGFBP2 in SHH medulloblastoma was worthy of investigation." (PMID 37029430, 2023). "Here we report elevated levels of IGFBP2 protein in the SHH group of medulloblastoma based on our studies in MB patient tumor cells, human and mouse MB cell lines and mouse primary MB cells." (PMID 37029430, 2023). "Single cell RNA sequencing analysis of Smo mutant mouse medulloblastoma shows IGFBP2 expression in tumor cells and microenvironment components including astrocytes, oligodendrocytes, and perivascular fibroblasts." (PMID 37029430, 2023). "We detected IGFBP2 at ~ 35 kDa molecular weight in Medulloblastoma samples." (PMID 37029430, 2023). "Future studies using cell- and tissue-specific IGFBP2 ablation will lead to insight as to how IGFBP2 produced by each of these cell types contributes to the overall tumor milieu; the present study focuses on the function of IGFBP2 produced by medulloblastoma tumor cells." (PMID 37029430, 2023). "It has been previously reported that IGFBP2 and IGFBP3 mRNA expression is elevated in medulloblastoma and correlates with poor prognosis." (PMID 37029430, 2023). "IGFBP2 is a pleiotropic member of the IGFBP super-family with secreted and intracellular functions that can modulate tumor cell proliferation, metastasis, and drug resistance, but has been understudied in medulloblastoma." (PMID 37029430, 2023). "Next, we confirmed that IGFBP2 upregulation is conserved in mouse models for SHH medulloblastoma, using cytokine array analysis of conditioned media from NeuroD2: Smo/A1 mouse primary medulloblastoma cells and SHH mouse medulloblastoma cell line, PZp53Med." (PMID 37029430, 2023). "Indeed, a literature search revealed only two publications: an immunohistochemistry study that reported no IGFBP2 in medulloblastoma, and a gene expression study finding significant-up-regulation of IGFBP2 in medulloblastoma and a link to poor prognosis." (PMID 37029430, 2023). "We also carried out western blotting of medulloblastoma and adjacent non-tumor tissue from NeuroD2: Smo/A1 mice, and we observed higher levels of IGFBP2 in tumor tissue; its levels were very low by comparison in a mouse model for Myc-amplified non-SHH medulloblastoma." (PMID 37029430, 2023). "While several proteins demonstrated enrichment, IGFBP2 was chosen for further analysis due to higher enrichment levels in SHH MB, its known roles in regulation of tumorigenicity and metastasis in other cancers, and lack of conclusive previous studies in medulloblastoma." (PMID 37029430, 2023).
microcephaly (4 papers, 2019 to 2022). A congenital or acquired developmental disorder in which the circumference of the head is smaller than normal for the person's age and sex. "Because IGFBP2 and ID4 maintain NSCs as well as regulate cerebral and cognitive development, IGFBP2 and ID4 dysregulation during NGLY1-defective cortical development could limit proliferation and cause premature differentiation in NSCs, which may underlie microcephaly in NGLY1-deficiency patients." (PMID 35322011, 2022).
multiple sclerosis (4 papers, 2013 to 2026). A progressive autoimmune disorder affecting the central nervous system resulting in demyelination. "IGFBP2 is also expressed in microglia in active lesions in multiple sclerosis cases." (PMID 31417357, 2019).
prediabetes (4 papers, 2022 to 2025). "For example, a study reported that low IGFBP2 was the strongest predictor for prediabetes (OR: 7.5) in women, while in men, the strongest predictor was IGFBP1 (OR: 13.4)." (PMID 39458471, 2024). "As for women, levels of adiponectin, IGFBP-1 and IGFBP-2 were significantly lower at baseline in those who later developed prediabetes or T2D as compared to controls." (PMID 36686443, 2022). "In NGT women the OR for prediabetes was highest for low IGFBP-2 (OR:7.48), closely followed by low adiponectin (OR:6.06)." (PMID 36686443, 2022). "In women the strongest predictor for T2D was adiponectin and in men IGFBP-1, and for prediabetes IGFBP-2 in women and IGFBP-1 in men." (PMID 36686443, 2022). "In women, low IGFBP-2 was the strongest predictor for prediabetes (OR:7.5), and low adiponectin for T2D (OR:29.4)." (PMID 36686443, 2022). "Conversely, baseline levels of adiponectin, IGFBP-1 and IGFBP-2 were significantly lower in individuals, who later developed prediabetes or T2D compared to the controls." (PMID 36686443, 2022). "For the prediction of prediabetes, only IGFBP-1 (OR:13.44) and IGFBP-2 (OR:4.03) yielded significant ORs." (PMID 36686443, 2022). "The strongest predictor for prediabetes was in men low IGFBP-1 and in women low IGFBP-2." (PMID 36686443, 2022).
Abdominal obesity (3 papers, 2021). Excessive fat around the stomach and abdomen. "Accordingly, a study reported that IGFBP2 DNA methylation is increased in visceral adipose tissue than in subcutaneous adipose tissue in 24 obese subjects, suggesting an epigenetic regulation of IGFBP2 in abdominal obesity." (PMID 33498859, 2021). "IGFBP2 is a cytokine secreted by differentiating white adipocytes and is regulated by DNA methylation in human abdominal obesity." (PMID 33614638, 2021).
acute coronary syndrome (3 papers, 2023 to 2024). Signs and symptoms related to acute ischemia of the myocardium secondary to coronary artery disease. "It is interesting to note that after differentiation, IGFBP2 changes from being upregulated in females to being upregulated in males—high IGFBP2 levels are associated with the development of major adverse cardiovascular events following acute coronary syndrome." (PMID 39796045, 2024). "Additionally, elevated IGFBP-2 levels in acute coronary syndrome patients correlate with low ejection fraction and a heightened risk of major cardiovascular complications." (PMID 39585162, 2024).
acute leukemia (3 papers, 2013 to 2024). A clonal (malignant) hematopoietic disorder with an acute onset, affecting the bone marrow and the peripheral blood. "IGFBP2 is a critical cell-autonomous factor that promotes the survival and migration of acute leukemia cells." (PMID 24191913, 2013). "We determined that IGFBP2 supports the survival and migration of acute leukemia cells in a cell-autonomous manner." (PMID 24191913, 2013). "In addition, HSCs and acute leukemia cells represent different cell identities and likely have very different signaling networks and thus use distinctive mechanisms to utilize IGFBP2." (PMID 24191913, 2013). "It is rather surprising that IGFBP2, a non-essential factor for normal development, is detrimental for acute leukemia cells upon deletion." (PMID 24191913, 2013). "There was also an increase in IGFBP-2 levels, while there is no direct evidence of the relationship between IGFBP-2 and CLL, it is highly expressed in certain human acute leukemia cells, and it supports the activity of hematopoietic stem cells (HSCs)." (PMID 38918490, 2024).
clear cell renal carcinoma (3 papers, 2022 to 2024). A malignant epithelial neoplasm of the kidney characterized by the presence of lipid-containing clear cells within a vascular network. "The expression of CNV-deficient m6A regulators IGFBP2 and ZC3H13 clear cell renal cell carcinoma was significantly reduced." (PMID 35281520, 2022). "The finding that LAMA4, BIRC7, GALNTL6, WNK2, and IGFBP2 are potential targets of miR-217 at different times of tumor evolution may help to develop stage-specific strategies, taking into account the differential expression of miR-217 in each stage of clear cell renal carcinoma progression." (PMID 35936681, 2022).
coronary heart disease (3 papers, 2021 to 2023). "Elevated levels of IGFBP2 were associated with death from ischemic heart disease and were also a biomarker of increased mortality in elderly subjects." (PMID 33686453, 2021).
dilated cardiomyopathy (3 papers, 2020 to 2023). Cardiomyopathy which is characterized by dilation and contractile dysfunction of the left and right ventricles. "IGFBP2 plays an important role in the IGF growth axis, with elevated levels associated with lower fasting insulin and fasting glucose, but with greater mortality in older adults and in patients with dilated cardiomyopathy." (PMID 33019943, 2020).
Hypoglycemia (3 papers, 2021 to 2025). A decreased concentration of glucose in the blood. "This molecule preferentially binds to IGF-binding protein-2 (IGFBP-2), forming an abnormal binary complex that interacts with insulin receptors, thereby inducing hypoglycemia." (PMID 41573654, 2025).
interstitial lung disease (3 papers, 2016 to 2025). A diverse group of lung diseases that affect the lung parenchyma. "There is however a previous report of increased IGFBP-2 in BAL of children with diverse interstitial lung diseases." (PMID 28178340, 2017). "Additionally, elevated serum IGFBP-2 levels have been detected in systemic sclerosis-associated interstitial lung disease (SSc-ILD), and are associated with deterioration of lung function, while treatment with anti-fibrotic agents pirfenidone and nintedanib reduces serum IGFBP-2." (PMID 41226289, 2025). "Moreover, IGFBP-2 was found at significantly higher level in the bronchoalveolar lavage of children with interstitial lung disease relative to healthy subjects." (PMID 27215343, 2016). "Previous studies focusing on IGFBP-2 in fibrosis showed an increase of IGFBP-2 in the bronchoalveolar lavage and in the lung tissue of patients with interstitial lung disease (ILD) without focusing on IPF." (PMID 27215343, 2016).